TRPS1 (transcriptional repressor GATA binding 1)
Diseases named in the same sentence as TRPS1 in open-access papers (continued):
Sharing a sentence is not in itself a finding about the gene and the disease.
colon cancer (6 papers, 2013 to 2024). "Further TRPS1 mutations were detected in additional colon cancer cases, correlating with advanced-stage disease and inferior prognosis." (PMID 39307879, 2024). "Recent studies have also confirmed that high TRPS1 expression was significantly associated with lymph node metastasis and higher pathological stage of patients with colon cancer." (PMID 24934762, 2014). "High TRPS1 expression was significantly associated with positive lymph node metastasis (P = 0.006) and higher pathological stage (P = 0.008) of patients with colon cancer." (PMID 23762846, 2013). "The high TRPS1 expression was significantly associated with positive lymph node metastasis (P = 0.006) and higher pathological stage (P = 0.008) of patients with colon cancer." (PMID 23762846, 2013). "We are unable to perfectly classify a single sample directly, but we have further investigated the relationship between colorectal cancer patients with TRPS1 gene mutations and several key molecular subtypes of colon cancer, validating our findings through comprehensive multi-omics analysis." (PMID 39307879, 2024). "On the basis of these findings, our data here also revealed the clinical relevance of TRPS1 expression to progression and prognosis of colon cancer." (PMID 23762846, 2013). "The aim of this study was to detect the expression pattern of TRPS1 in human colon cancer and to analyze its correlation with prognosis of patients with this disease." (PMID 23762846, 2013). "In the current study, we detected the expression of TRPS1 at both mRNA and protein levels and then explored its prognostic value by using complete long-term follow-up data of a cohort of colon cancer samples." (PMID 23762846, 2013). "TRPS1 was expressed in the nucleus of colon cancer cells in 63/100 (63.0%) of cases with unequal intensity." (PMID 23762846, 2013). "The protein level of TRPS1 in colon cancer tissues was significantly correlated with the mRNA level (r = 0.9, P < 0.001)." (PMID 23762846, 2013). "This is the first report to suggest a relationship between TRPS1 overexpression and prognosis in patients with colon cancer, and further prospective analysis would be worth doing." (PMID 23762846, 2013). "Statistical analysis also indicated that the protein expression levels of TRPS1 were significantly higher in colon cancer tissues compared with their normal counterparts (3.8 ± 0.3 versus 1.3 ± 0.4, P < 0.001)." (PMID 23762846, 2013). "Recent studies investigating the relationship between Trps1 and tumor malignancy have revealed reduced cellular expression levels of Trps1 at the primary sites of endometrial carcinoma and breast, prostate, pancreatic, and colon cancers." (PMID 25886207, 2015). "Collectively, our data suggest that TRPS1 might represent a novel indicator for the prognosis of colon cancer." (PMID 23762846, 2013). "In conclusion, our data offer the convinced evidence for the first time that the increased expression of TRPS1 may be involved in the pathogenesis and progression of colon cancer." (PMID 23762846, 2013). "Additionally, immunohistochemistry analysis also found increased TRPS1 expression in 63.0% (63/100) of colon cancer tissues." (PMID 23762846, 2013). "However, the mechanisms by which TRPS1 is aberrantly expressed in colon cancer need further investigation." (PMID 23762846, 2013). "In order to analyze the correlation of TRPS1 expression with various clinicopathological characteristics of patients with colon cancer, we divided 100 patients into two groups according to the expression levels of TRPS1 protein detected by immunohistochemistry." (PMID 23762846, 2013). "Furthermore, colon cancer patients with high TRPS1 expression had shorter overall survival than those with low TRPS1 expression." (PMID 23762846, 2013). "Finally, TRPS1 may promote metastatic polyclonal seeding in colon cancer by enhancing epithelial-to-mesenchymal transition." (PMID 39307879, 2024).
colon cancer (continued). "TRPS1 might be a potential marker to predict the prognosis in colon cancer." (PMID 23762846, 2013). "We found that TRPS1 mRNA was expressed at a high level in colon cancer tissues compared with matched noncancerous colon tissues (4.1 ± 0.5 versus 1.6 ± 0.5, P < 0.001)." (PMID 23762846, 2013). "The expression of TRPS1 mRNA in 20 pairs of colon cancer and their matched noncancerous colon tissues was detected by qRT-PCR." (PMID 23762846, 2013). "The results showed that TRPS1 mRNA and protein expression were both significantly upregulated in colon cancer tissues as compared with their corresponding noncancerous colon tissues." (PMID 23762846, 2013).
hypertrichosis (6 papers, 2012 to 2024). Excessive hair growth anywhere on the body. "We previously demonstrated that a position effect on the zinc-finger transcription factor TRPS1 is associated with two hypertrichosis models, Ambras syndrome (AS) in humans and the Koala phenotype in mice." (PMID 23133399, 2012). "Consistent with a causative role for Trps1 in hypertrichosis, the protein is expressed in the nuclei of mesenchyme-derived dermal papilla cells and the proliferative epithelial cells of human and mouse hair follicles." (PMID 23133399, 2012). "We have previously demonstrated that a position effect on TRPS1 is associated with hypertrichosis in both humans and mice, providing the first evidence for a position effect associated with abnormalities in hair follicle development." (PMID 23133399, 2012). "We previously demonstrated that a position effect on TRPS1 is associated with cases of hypertrichosis in both humans and mice." (PMID 23133399, 2012). "We have previously demonstrated that a position effect on TRPS1 is associated with hypertrichosis in humans and mice." (PMID 23133399, 2012). "A previous study found that hair growth of Inner Mongolia Cashmere goats was regulated by the hypertrichosis gene TRPS1, which is similar to our study outcomes." (PMID 33080940, 2020). "Here, we establish that a position effect on the Trps1 target gene SOX9 is likely involved in the pathology of human hypertrichosis." (PMID 23133399, 2012). "The TRPS1 (Transcriptional Repressor GATA Binding 1) gene has been suggested as a strong candidate gene for hair development, developing hair follicles, and is associated with hypertrichosis." (PMID 39570887, 2024). "Hair growth was considered to be regulated by hairless gene, FOXI313, hypertrichosis gene, FGF13, Trps1, Sox914, 15, and hair overgrowth gene, ABCA516." (PMID 27796358, 2016).
lung carcinoma (6 papers, 2018 to 2025). "The report has shown the association of TRPS1 (Tricho-rhino-phalangeal syndrome 1) with MDR (multidrug resistance) in lung cancer." (PMID 35885958, 2022). "While the initial studies showed a low expression of TRPS1 in lung cancers, more recent studies demonstrated that a significant proportion of lung cancers showed TRPS1 expression." (PMID 40025593, 2025). "Instead, the primary value of TRPS1 in lung cancer diagnostics lies in its ability to exclude metastatic breast cancer in cases where primary lung adenocarcinoma is suspected." (PMID 39518009, 2024). "It was determined that the miRNA expression of genes CDK19, SAMD8, TBL1XR1, and TRPS1 were significantly upregulated in the LUSC dataset between lung cancer patients and controls." (PMID 35885958, 2022). "TRPS1 is also highly expressed in lung cancer and is involved in regulating epithelial-to-mesenchymal transition (EMT) during embryonic development." (PMID 33902609, 2021). "Taken together, our data verify that Trps1 gene is an up mediator of MGMT gene, and Trps1 enhanced antidrug abilities of lung cancer cells are at less partially contributed by MGMT." (PMID 29601666, 2018). "Multidrug resistance (MDR) often leads to chemotherapy failure of lung cancer and has been linking to the cellular expression of several DNA transcription‐ and repair‐related genes such as Trps1 and MGMT." (PMID 29601666, 2018). "Taken together, we consider that upregulation of Trps1 induces MGMT transcription contributing to the formation of MDR in lung cancer cells." (PMID 29601666, 2018). "Expression of TRPS1 was also demonstrated in lung cancers at a molecular level." (PMID 40025593, 2025). "Data pertaining to immunoexpression of TRPS1 in lung cancers is scarce and variable." (PMID 40025593, 2025). "However, the absence of TRPS1 in primary lung cancers limits its utility as a standalone diagnostic marker in these cases." (PMID 39518009, 2024). "Therefore, given the transcriptional activity of Trps1, whether Trps1 regulates MGMT expression is quite a significant question for the development of MDR in lung cancer." (PMID 29601666, 2018). "This highlights the importance of using TRPS1 in conjunction with other markers, such as TTF-1 and Napsin A, which are specific for primary lung cancers." (PMID 39518009, 2024). "In the present study, we occasionally found that Trps1 and MGMT expressions both increased in cisplatin‐resistant lung cancer cells (H446/CDDP)." (PMID 29601666, 2018). "TRPS1 expression has been studied in lung cancer and, interestingly, TRPS1 is typically not expressed in primary lung cancers, making it a useful marker for distinguishing metastatic breast cancer from primary lung adenocarcinoma." (PMID 39518009, 2024). "In our previous study, we have occasionally found a positive correlation between MGMT and Trps1 in lung cancer cells (data not show)." (PMID 29601666, 2018). "To elucidate the regulating effect of Trps1 on MGMT expression in lung cancer, we detected the functional interactions between Trps1 and MGMT in a typical small cell lung cancer cell line (H446) by both downregulation and upregulation of Trps1 or MGMT, respectively." (PMID 29601666, 2018).
squamous cell carcinoma (6 papers, 2022 to 2025). A carcinoma arising from squamous epithelial cells. "Embryologic similarities among skin adnexa, breast, and salivary glands underlie TRPS1’s expression in diverse neoplasms, including cutaneous adnexal tumors, squamous cell carcinoma, and reactive fibroblasts/myofibroblasts in scars." (PMID 40969274, 2025). "TRPS1 expression has also been observed in a variety of tumors including cutaneous adnexal tumors, squamous cell carcinoma, and mammary Paget disease." (PMID 41463263, 2025). "Robust TRPS1 expression has been observed in various cutaneous epithelial neoplasms, including squamous cell carcinomas, mammary and extramammary Paget diseases, and adnexal neoplasms." (PMID 39051323, 2024). "Additionally, we included selected cases of melanoma with spindled cell morphology or desmoplastic features (n = 9) and sarcomatoid squamous cell carcinoma (SSCC) (n = 5) to compare TRPS1 expression patterns with those of AFX." (PMID 39051323, 2024). "Moreover, TRPS1 was shown to be expressed in skin tumors (including squamous cell carcinoma), therefore, it is not clear if TRPS1 positivity in metaplastic cancers represents a true breast specific expression or just because of squamous/mesenchymal differentiation." (PMID 40025593, 2025).
endometrial carcinoma (5 papers, 2015 to 2025). A malignant tumor arising from the epithelium that lines the cavity of the uterine body. "In Ishikawa, Loss of TRPS1 significantly prompted the growth of endometrial cancer, and impaired the inhibitory effect of MPA on it." (PMID 37344459, 2023). "In endometrial carcinoma, TRPS1 expression has been reported in a range of between 12.3% to 71% of all tumors." (PMID 39518009, 2024). "Dissecting the relationship between PR cofactor recruitment and histone modification will improve our understanding of the complex selective mechanisms of progesterone and assist us to identify TRPS1 as a potential marker for personalized therapeutic strategies in endometrial carcinoma." (PMID 37344459, 2023). "Moreover, we also verified the complicated role of TRPS1 in tumor xenograft models and found that TRPS1 overexpression resulted in a potent decrease of cell growth when coupled with MPA in endometrial cancer, and loss of TRPS1 expression in BC cells showed reduced MPA-mediated growth pattern." (PMID 37344459, 2023).
Langer-Giedion syndrome (5 papers, 2008 to 2026). "Six probes were screened in the 8q24 region associated with Langer-Giedion syndrome, in TRPS1 (2 probes), EIF3S3 (1 probe), EXT1 (2 probes) and SAMD12 (1 probe)." (PMID 18925931, 2008). "Langer-Giedion syndrome (LGS), also known as trichorhinophalangeal syndrome type II (TRPS II; OMIM #150230), is a contiguous-gene deletion disorder caused by haploinsufficiency of TRPS1 and EXT1." (PMID 41751561, 2026). "Langer–Giedion syndrome (LGS), also known as Trichorhinophalangeal Syndrome Type II (TRPSII) (OMIM 150230), is a rare contiguous gene syndrome caused by a deletion involving loss of functional copies of TRPS1 and EXT1." (PMID 32296131, 2020). "Langer-Giedion syndrome (LGS) or TRPS type II is a contiguous gene syndrome on 8q24.1, involving loss of functional copies of the TRPS1 and EXT1 genes." (PMID 26269715, 2015). "A deletion in chromosome 8q24.11 or 8q23.3-q24.13, which contains EXT1, but not TRPS1, also causes Langer-Giedion syndrome." (PMID 34539746, 2021).
melanoma (5 papers, 2017 to 2025). A malignant, usually aggressive tumor composed of atypical, neoplastic melanocytes. "No other exonic variants were detected that have previously been implicated in melanoma, although high-level mutations were detected in tumour suppressor genes (TRPS1 and CSMD1), pinpointing to their role as potential disease drivers in this patient." (PMID 29075515, 2017). "However, molecular studies are time-consuming, and therefore future studies to identify TRPS1 staining in melanoma can be very helpful." (PMID 40025593, 2025). "TRPS1 is rarely expressed in some types of tumors, including urothelial carcinoma, lung adenocarcinoma, pancreatic cancer, colorectal and gastric adenocarcinoma, and melanoma." (PMID 40822238, 2025). "Our findings indicate that the presence of strong and diffuse TRPS1 expression may lean towards a diagnosis of AFX over angiosarcoma or melanoma, provided it is supported by other commonly used discriminatory immunohistochemical markers like ERG and SOX10." (PMID 39051323, 2024). "In our limited validation cohort (not included in the study cohort), we noted one case of melanoma with diffuse TRPS1 expression, however, a conclusive comment cannot be made without a large-scale study." (PMID 40025593, 2025). "Intrigued by these findings, particularly the frequent expression of TRPS1 in the AFX/PDS group, we extended our investigation to include morphological mimics, such as sarcomatoid SCCs and melanomas, especially those exhibiting spindled cell morphology or desmoplastic features." (PMID 39051323, 2024). "Given that sarcomatoid SCCs, melanomas, leiomyosarcomas, and angiosarcomas are frequently considered in the morphological differential diagnosis of AFX, the TRPS1 expression characteristics of the AFX/PDS group were compared with those of the former three entities." (PMID 39051323, 2024).
mesenchymal tumors (5 papers, 2024 to 2025). "While TRPS1 positivity is documented in mammary/extramammary Paget disease and mesenchymal tumors, its diagnostic utility in PCMC requires contextual integration." (PMID 40969274, 2025). "Regarding other mesenchymal tumors, Cloutier and colleagues observed heightened TRPS1 expression in both primary and metastatic synovial sarcomas." (PMID 38902365, 2025). "TRPS1 has been recognized as a sensitive marker for tumors of breast origin and mesenchymal tumors arising in breast parenchyma." (PMID 41463263, 2025). "In this study, our objective was to assess the immunohistochemical expression patterns of TRPS1 in a subset of mesenchymal neoplasms and tumors of uncertain differentiation originating in the skin." (PMID 39051323, 2024). "In conclusion, our study has provided novel insights into the TRPS1 expression patterns in a subset of cutaneous mesenchymal tumors and tumors of uncertain differentiation." (PMID 39051323, 2024). "However, to our knowledge, there has been limited investigation into the TRPS1 immunoreactivity status in cutaneous mesenchymal tumors and tumors of uncertain differentiation, such as AFXs or PDSs." (PMID 39051323, 2024). "Additionally, Wang and his colleagues explored TRPS1 immunohistochemistry in mesenchymal tumors." (PMID 38902365, 2025). "Our study has some limitations, including namely the relatively small size of the cohort studied and the low representation of some TRPS1-positive tumor types, such as metastases from SCC and from mesenchymal tumors such as leiomyosarcomas." (PMID 39449380, 2024).
metastatic carcinoma (4 papers, 2024 to 2025). A carcinoma which has spread from the original site of growth to another anatomic site. "In the remaining 89 cases, TRPS1 IHC was utilized in the diagnostic work-up for distant metastasis to determine whether the metastatic carcinoma was breast origin (n = 80) or from other sites (n = 9)." (PMID 40025593, 2025). "A study evaluated the utility of TRPS1 in the differential diagnosis of malignant pleural effusion found a high immunoreactivity of TRPS1 in metastatic carcinomas of tubo-ovarain origin/high grade serous carcinoma (75%)." (PMID 40025593, 2025). "Conversely, TRPS1 positivity was noted in metastatic cancers of lung, bladder and Mullerian origin, making its usage as a sole breast marker questionable." (PMID 40025593, 2025). "We present here the largest cohort of metastatic carcinomas to the skin studied for the expression of TRPS1." (PMID 39449380, 2024). "However, its expression in soft tissue tumors may complicate the use of TRPS1 in distinguishing synovial sarcoma from metastatic carcinomas, particularly when a sarcomatoid carcinoma metastasis is considered in differential diagnoses of spindle cell tumors." (PMID 39518009, 2024). "The combined application of TRPS1 and GATA3 is the optimal method to confirm that ER-negative or low-expression distant metastatic carcinoma originates from the breast." (PMID 40822238, 2025). "The combined application of TRPS1 and GATA3 is the best method to determine breast origin of ER-negative or low-expression distant metastatic cancers." (PMID 40822238, 2025). "Nevertheless, TRPS1 and GATA3 could be a reliable panel to determine the breast origin of metastatic cancer." (PMID 40822238, 2025).
phyllodes tumor (4 papers, 2024 to 2025). A benign, borderline, or malignant fibroepithelial neoplasm arising from the breast and rarely the prostate gland. "While these findings also imply lack of utility of TRPS1 in differentiating metaplastic carcinoma vs. phyllodes tumor, more studies are required to prove this assumption." (PMID 40025593, 2025). "TRPS1 expression has also been observed in the sarcomatous component of malignant phyllodes tumors in 95% of cases, regardless of if the sarcomatous component was chondro-osseous, liposarcomatous, or spindle cell." (PMID 39518009, 2024).
urothelial carcinoma (4 papers, 2025 to 2026). A malignant neoplasm derived from the transitional epithelium of the urinary tract (urinary bladder, ureter, urethra, or renal pelvis). "In a very recently published paper by Bachert and colleagues, TRPS1 expression was reported at a rate of approximately 31% and 27% in prostate and urothelial carcinomas, respectively." (PMID 38902365, 2025). "A recent study demonstrated that 24.6% prostatic adenocarcinoma and 20.5% urothelial carcinomas expressed TRPS1." (PMID 40025593, 2025). "Unlike GATA3, TRPS1 is not expressed in urothelial carcinoma." (PMID 40025593, 2025).